ALK (ALK receptor tyrosine kinase)
Diseases named in the same sentence as ALK in open-access papers (continued):
Sharing a sentence is not in itself a finding about the gene and the disease.
neuroblastoma (continued). "Anaplastic Lymphoma Kinase (ALK) was upregulated in advanced/metastatic neuroblastomas, and furthermore, treatment of ALK-positive neuroblastoma cells with tunicamycin, an inhibitor of N-glycosylation, impaired the pro-survival signaling pathway." (PMID 32260356, 2020). "Anaplastic lymphoma kinase (ALK), an oncogene expressed in neuroblastoma cells, is associated with familial neuroblastoma cases." (PMID 33322408, 2020). "In particular, in neuroblastoma, ALK events cooperate with MYCN amplification to accelerate neuroblastoma development and progression." (PMID 32059449, 2020). "Activating mutations in the anaplastic lymphoma kinase (ALK) gene have been reported in 50% of familial NB (familial NB is rare accounting for around 2% of NB cases) and between 8 and 10% of sporadic neuroblastoma, across all risk groups and occurring more frequently at relapse." (PMID 32309213, 2020). "Treatment with crizotinib, employed as positive control, also reduced cell proliferation of ALK addicted neuroblastoma cells as previously reported." (PMID 31852910, 2019). "Here we investigate the pre-clinical potential of alectinib in an ALK positive neuroblastoma context." (PMID 31334113, 2019). "Together these results suggest that ALK is an accelerator and require other genetic insults in order to develop neuroblastoma." (PMID 30760980, 2019). "Three hotspot residues (F1174, F1245, and R1275) account for 85% of mutant ALK seen in neuroblastoma." (PMID 30778092, 2019). "The publicly available 11‐plex TMT dataset PXD009477 of ALK signaling in the neuroblastoma cell line NB1 was re‐analyzed using INKA." (PMID 30979792, 2019). "It is worthy to note that both zebrafish iridophores and human neuroblastoma, an embryonic tumor, derive from the neural crest, showing the importance of ALK and DrLtk in development." (PMID 30813562, 2019). "Based on this evidence, Lorlatinib is now available in an international study for children with relapsed ALK mutant neuroblastoma." (PMID 35582571, 2019). "Initial clinical trial results have shown that it is difficult to inhibit growth of ALK positive neuroblastoma with crizotinib, motivating investigation of next generation ALK inhibitors with higher affinity for ALK." (PMID 31334113, 2019). "With this background, a clinical trial with lorlatinib in ALK-driven neuroblastoma is now being conducted by New Approaches to Neuroblastoma Therapy (NANT) Consortium (NCT03107988)." (PMID 31747416, 2019). "Other ALK inhibitors demonstrating good preclinical rationale for neuroblastoma include Alectinib and Entrectinib." (PMID 35582571, 2019). "Alterations in the ALK gene are found in both familial and sporadic neuroblastoma cases, and at a higher frequency in the relapsed patient population." (PMID 31852910, 2019). "Entrectinib inhibits both ALK and the TRK receptors; TRKb is associated with poor prognosis in neuroblastoma." (PMID 35582571, 2019). "Mechanistically, ERK5 is activated by the anaplastic lymphoma kinase (ALK), an important molecular target in neuroblastoma, through PI3K, AKT, and MEKK3–MEK5–ERK5 signaling pathways." (PMID 30901834, 2019). "A phase I clinical trial of the first generation ALK inhibitor, crizotinib, in neuroblastoma patients showed modest results and suggested that further investigation was needed." (PMID 31852910, 2019). "Here we have investigated the ability of alectinib to abrogate the activity of ALK gain of function mutations found in neuroblastoma patients, examining this ALK TKI in ALK positive neuroblastoma cell lines, and in ALK driven xenografts." (PMID 31334113, 2019). "Next generation ALK TKIs such as lorlatinib and brigatinib have been shown to be more effective than crizotinib as single agent neuroblastoma xenografts." (PMID 31334113, 2019).
neuroblastoma (continued). "In contrast to the situation with MYCN amplification, ALK is the first kinase identified as a driver in neuroblastoma with real potential as a tractable therapeutic target, due to the number of inhibitors already available." (PMID 35582571, 2019). "The ALK expression level measured at the single-cell level in the three analyzed cell lines is consistent with the previous description of an increased ALK expression in neuroblastoma samples with activated ALK compared to samples with WT ALK." (PMID 31452835, 2019). "For instance, two ALK constitutively-active mutants, F1174L and R1275Q, were frequently found in neuroblastomas, which accounts for 15% of all childhood cancer deaths." (PMID 30726988, 2019). "In neuroblastoma cell proliferation assays, the IC50 values observed with repotrectinib are in the same range as crizotinib, and repotrectinib is able to inhibit ALK phosphorylation over a wide range of ALK mutant variants found in neuroblastoma." (PMID 31852910, 2019). "Treatment with repotrectinib as a single agent in human ALK-addicted cell line neuroblastoma xenografts resulted in robust tumor growth reduction." (PMID 31852910, 2019). "The availability of later-generation ALK-targeted therapeutics has led to a unique situation for pediatric neuroblastoma patients." (PMID 35582571, 2019). "This includes the use of MEK inhibitors in relapsed CNS tumors with BRAF fusion, use of crizotinib, or other ALK inhibitors in relapsed neuroblastoma with an ALK alteration, and the use of imatinib and dasatinib in Ph (+) ALL." (PMID 31133068, 2019). "Employing neuroblastoma cell lines and mouse xenografts we show a clear and efficient inhibition of ALK activity by alectinib." (PMID 31334113, 2019). "Here, alectinib, a potent next generation ALK inhibitor with antitumor activity was investigated in ALK-driven neuroblastoma models." (PMID 31334113, 2019). "Here we show that repotrectinib inhibits cell proliferation in neuroblastoma cells that are dependent on ALK for growth, such as CLB-BAR, CLB-GE and Kelly cells." (PMID 31852910, 2019). "As examples, in the PPTC dataset, GPC2 and ALK are dramatically overexpressed neuroblastoma models, as previously published, but also in multiple subsets of additional pediatric cancer histotypes, allowing for a basket trial design for preclinical testing." (PMID 31693904, 2019). "Of note, PIM inhibition sensitized both MYCN-amplified and wild-type, ALK-driven neuroblastoma cells to ALK inhibitors both in vitro and in vivo, suggesting co-inhibition of PIM and ALK as a viable strategy to enhance the efficacy of ALK inhibitors." (PMID 31780656, 2019). "Taken together, the repotrectinib inhibition profiles observed for ALK-Y1604 phosphorylation and ALK driven PC-12 cell neurite outgrowth show that this ALK TKI is able to inhibit a wide range of active ALK neuroblastoma mutants." (PMID 31852910, 2019). "The first clinical use of alectinib in a case of heavily pretreated, refractory metastatic ALK positive neuroblastoma was recently published." (PMID 31334113, 2019). "Palmer’s group showed that both FAM150A and FAM150B were not only able to bind and activate human wild type ALK, but also constitutively active ALK mutants from neuroblastoma, resulting in a further enhanced activity or ‘superactivation’." (PMID 30813562, 2019). "Crizotinib, a 1st generation ALK inhibitor, has been reported to have potency in in vitro studies with neuroblastoma cell lines, and it has been tested in a Phase I clinical trial for the treatment of pediatric solid tumors." (PMID 31747416, 2019). "For example, neuroblastoma cells treated with ALK-activating monoclonal antibodies or with FAM150 ligands promote cell proliferation or differentiation while activating the ERK1/2 and ERK5 pathways." (PMID 30813562, 2019). "We verified the endogenous NUMB–ALK interaction by co-immunoprecipitation (Co-IP) in the IMR-5 cells, a neuroblastoma cell line expressing wild-type ALK." (PMID 30726988, 2019).
neuroblastoma (continued). "The opportunity to manipulate ALK activity in neuroblastomas is complicated by the specificity of individual ALK mutants for available compounds." (PMID 35582571, 2019). "Although numerous mutations in ALK have been identified, three “hot spots” in the ALK kinase domain at residues F1174, F1245 and R1275 account for the majority of ALK aberrations in neuroblastoma patients." (PMID 31852910, 2019). "Neuroblastoma cell lines were treated with repotrectinib to investigate inhibition of ALK and to determine its effect on proliferation." (PMID 31852910, 2019). "Taken together, our results indicate that alectinib is an effective inhibitor in an ALK-positive neuroblastoma setting." (PMID 31334113, 2019). "In anticipation of resistance to ALK inhibition and in order to improve the best response for patients with ALK mutant neuroblastoma, combination clinical studies are already underway." (PMID 35582571, 2019). "Our aim was to evaluate to what extent several of these well-established driver genes (MYCN, ALK) and neuroblastoma identity genes (PHOX2B) impact lincRNA expression." (PMID 30952905, 2019). "Of note, though the average cell death rate in non-neuroblastoma and non-ALK expressing cell lines (RD and VH7) was below 10% for all treatment conditions, crizotinib treatment increased the amount of dead cells, presumably by interacting with c-MET." (PMID 29515255, 2018). "The induction of autophagy has been demonstrated in certain neuroblastoma cell lines when treated with the ALK inhibitor, entrectinib." (PMID 30326621, 2018). "When our group engineered a CAR against Anaplastic Lymphoma Kinase (ALK) on neuroblastoma, there was a clear correlation between the number of surface molecules of target antigen and ALK CAR T cell efficacy." (PMID 30459759, 2018). "ALK amplification has also been reported in neuroblastoma almost invariably together with amplification of the adjacent gene MYCN, with possible synergic effects in driving cell growth and survival." (PMID 29495603, 2018). "The possible therapeutic use of CAR T cells directed against the extracellular domain of ALK is being explored against ALK-expressing neuroblastoma." (PMID 29642597, 2018). "This encouraging data led to a phase 1 trial of loratinib for patients with ALK aberrant neuroblastoma that is currently ongoing through the NANT consortium (NCT03107988)." (PMID 30326621, 2018). "All neuroblastoma cell lines expressed ALK, with strong expression in LAN-5 cells and amplification in NB-1 cells, whereas the other target of crizotinib, c-MET, was not expressed." (PMID 29515255, 2018). "We find that pY-GSK3 phosphorylation depends on anaplastic lymphoma kinase (ALK), a protein associated with neuroblastoma." (PMID 29555900, 2018). "Of note, high expression of ALK is a frequent observation in paediatric neuroectodermal tumours and neuroblastoma." (PMID 29642598, 2018). "These ALK inhibitors continued to be explored in neuroblastoma and include: ceritinib, ensartinib, entrectinib, lorlatinib and alecintib." (PMID 30326621, 2018). "Further, inhibition of N-glycosylation in ALK-positive neuroblastoma cells, via tunicamycin treatment, disrupted the pro-survival signaling pathway." (PMID 29902282, 2018). "Targeted therapies have been developed for ALK+ neuroblastoma and others are in development for many of the genetic aberrations described." (PMID 30200332, 2018). "In neuroblastoma, ALK activity has been shown to promote transcription of MYCN through phosphorylation of ERK5, a member of the MAPK family, in a PI3K-dependant manner thus integrating ALK effector signaling and MYC regulation." (PMID 29507657, 2018). "In our analysis, we confirm this high frequency in MYCN (7/15 cases), ALK (4/5 of cases) and Lin28b (6/6 of cases) driven neuroblastoma models." (PMID 29492199, 2018).
neuroblastoma (continued). "ALK CAR T cells demonstrated in vitro activity but had limited efficacy in vivo in xenograft models of neuroblastoma." (PMID 30459759, 2018). "Several groups have identified anaplastic lymphoma kinase (ALK) as a potential oncogene in neuroblastoma." (PMID 30459759, 2018). "Regardless of amplification, ALK overexpression is widely observed in nearly 100% of basal cell carcinoma and in more than 50% of neuroblastomas, with only 10% of primary neuroblastomas displaying also ALK gene amplification." (PMID 29455642, 2018). "Investigations into the reasons for limited CAR efficacy demonstrated that ALK expression on the neuroblastoma cell lines used was below the threshold of antigen expression required for CAR activity." (PMID 30459759, 2018). "For instance, anaplastic lymphoma kinase (ALK) and PHOX2B gene variants are among the predisposing factors to familial neuroblastoma." (PMID 30285664, 2018). "ALK (anaplastic lymphoma receptor tyrosine kinase) gene alterations have been reported in various cancers including pediatric neuroblastomas." (PMID 29324814, 2018). "Here, we report on the further genomic characterization through exome sequencing and DNA copy number analysis of four of the currently available murine neuroblastoma model systems (ALK, Th-MYCN, Dbh-MYCN and Lin28b)." (PMID 29492199, 2018). "In neuroblastoma, ALK is almost ubiquitously expressed on the cell surface and expression is restricted to tumor cells." (PMID 29515255, 2018). "Anaplastic lymphoma kinase (ALK) is an oncogenic receptor tyrosine kinase that is activated by gene amplification and mutation in neuroblastomas." (PMID 29760954, 2018). "Three germline missense mutations (R1192P, R1275Q, and G1128A), were identified in the tyrosine kinase domain of ALK that were present in the majority of familial neuroblastoma cases evaluated." (PMID 30200332, 2018). "The effective dose of crizotinib in neuroblastoma cell lines ranged from 0.05 μM (ALK-amplified) to 0.8 μM (wildtype ALK)." (PMID 29515255, 2018). "Driver genes/alterations, such as MYCN, 1p/11q deletion, ALK, ATRX and TERT, are characterized in high-risk neuroblastoma by previous studies, however, it is difficult to further stratify the high-risk neuroblastoma at molecular level." (PMID 30405689, 2018). "The 1174 residue is found at the carboxyterminal end of the αC-helix and has been shown to reduce ALK sensitivity to crizotinib by increasing ATP binding affinity in neuroblastoma cell lines and in vivo models." (PMID 29495603, 2018). "More recent preclinical studies have demonstrated the failure of monotherapy with MEK inhibition in ALK-addicted neuroblastoma due to increased feedback activation of other signaling pathways including PI3K/AKT pathway." (PMID 30326621, 2018). "We identified receptor tyrosine kinases (RTKs), such as anaplastic lymphoma kinase (ALK), as druggable neuroblastoma cell survival activators that can be targeted by treatment with small molecule inhibitors, thus sensitizing neuroblastomas to HDAC8 inhibition." (PMID 29515255, 2018). "These cells were able to effectively kill HLA-matched ALCL and neuroblastoma cell lines endogenously expressing ALK." (PMID 29642597, 2018). "Whole chromosome 3 gains are a remarkably frequent recurring event in MYCN (46% of cases in our series, up to 40% of published cases), ALK (80% of cases) and Lin28b (100% of cases) driven murine neuroblastoma tumors." (PMID 29492199, 2018). "There are also reports of upregulation of Axl in anti-HER2-resistant breast cancer, unitinib-resistant renal cell cancer, and anaplastic lymphoma kinase (ALK) inhibitor-resistant neuroblastoma, as well as in head and neck cancer resistant to PI3K inhibitors." (PMID 30322068, 2018). "In neuroblastoma, constitutive activation of the tyrosine kinase domain of ALK by multiple possible genetic mechanisms results in increased oncogenicity." (PMID 30200332, 2018).
neuroblastoma (continued). "Further, N-glycosylation processing of ALK receptors, and the pro-survival signaling pathway were impaired by treatment of ALK-positive neuroblastoma cells with tunicamycin." (PMID 29902282, 2018). "Novel therapies targeting these neuroblastoma driver genes such as ALK inhibitors and inhibitors of the BRD4-MYCN-promotor interaction are already emerging." (PMID 30504901, 2018). "We assessed or re-assessed MYCN and ALK copy numbers in gDNA from a panel of 15 cell lines commonly used in neuroblastoma research during the development and validation of our ddPCR protocol." (PMID 29156716, 2017). "The efficacy of ALK inhibitors in patients with ALK-mutant neuroblastoma is limited, highlighting the need to improve their effectiveness in these patients." (PMID 28425916, 2017). "To this end, we sought to develop a combination strategy to enhance the antitumor activity of ALK inhibitor monotherapy in human neuroblastoma cell lines and xenograft models expressing activated ALK." (PMID 28425916, 2017). "In this regard, focal amplifications of ALK, CCND1, LIN28B, MDM2, and 19q13.42 observed in our study have been previously implicated in individual neuroblastoma studies 8–12." (PMID 28924153, 2017). "Together, these data indicate that the ALK immunoassays can be used to characterize basal levels of ALK activity in neuroblastoma cells in a more quantitative manner and with greater sensitivity than immunoblotting." (PMID 28432815, 2017). "We accurately assessed ALK copy numbers in the primary neuroblastomas from tumor-derived cfDNA in blood plasma samples." (PMID 29156716, 2017). "Here, we present ddPCR as an accurate method to assess MYCN and ALK copy numbers in tumor-derived cfDNA from blood plasma from neuroblastoma patients." (PMID 29156716, 2017). "In a final validation step, we accurately distinguished MYCN and ALK copy numbers of the corresponding primary tumors using retrospectively collected blood plasma samples from 10 neuroblastoma patients." (PMID 29156716, 2017). "A third genomic rearrangement (ALK-NEURL1) was detected in the plasma of a stage IV neuroblastoma patient (NB-pt03) and further confirmed by digital PCR, yielding similar VAFs (0.109 versus 0.069, respectively)." (PMID 28874686, 2017). "All these findings suggest that the challenge for treating ALK-driven neuroblastomas is to overcome de novo resistance and combinatorial therapies are required to maximize the clinical benefit of ALK inhibition in neuroblastoma with ALK aberrations." (PMID 28425916, 2017). "The observed unexpected upregulation of ADM warrants further investigation in relation to putative ALK resistance in neuroblastoma patients currently undergoing ALK inhibitor treatment." (PMID 29290991, 2017). "Among the six relatively poor prognostic markers, ALK and BARD1 have been reported as neuroblastoma predisposition genes." (PMID 28984200, 2017). "This study presents ddPCR as an accurate tool to assess MYCN and ALK copy numbers in neuroblastoma cell lines, tumor samples and tumor-derived cfDNA in blood plasma." (PMID 29156716, 2017). "Several elegant studies in transgenic zebrafish and mouse models have already demonstrated synergistic effect of expressing activated ALK together with MYCN on inducing neuroblastoma." (PMID 28425916, 2017). "We describe the early and late effects of ALK inhibitor TAE684 treatment on the neuroblastoma transcriptome." (PMID 29290991, 2017). "Very recently, CQ has been proposed as adjuvant in chemotherapy for neuroblastoma as its pro-autophagic role seemed to enhance the efficacy of the ALK inhibitor entrectinib." (PMID 29069774, 2017). "We analyzed ALK copy numbers relative to NAGK copy numbers using ddPCR of gDNA from our neuroblastoma cell line panel." (PMID 29156716, 2017). "In our study, several lines of evidence prompted us to assess the effectiveness of the combination of ceritinib and CGM097 in neuroblastoma models expressing activated ALK." (PMID 28425916, 2017).